COA4 (cytochrome c oxidase assembly factor 4 homolog)
Description:
Putative COX assembly factor.
Synonyms: CHCHD8; E2IG2; CMC3
Tractability: PROTAC: ubiquitination databases record sites on it.
Gene: Protein-coding gene on chromosome 11 (73,869,846 to 73,876,982, reverse strand). Ensembl gene ENSG00000181924.
Subcellular location: Mitochondrion
Subcellular location (Human Protein Atlas): Nucleoli fibrillar center; Nucleoplasm; Mitochondria
Pathways (Reactome):
Protein localization: Mitochondrial protein import
Gene Ontology:
Molecular function: protein binding
Biological process: mitochondrial respiratory chain complex IV assembly
Cellular component: mitochondrion; mitochondrial intermembrane space
Genetic constraint (gnomAD): Loss-of-function variants: 11 observed, 10.03 expected, observed/expected ratio (o/e) 1.1, 90% interval 0.69 to 1.74. The upper end of that interval is the gene's LOEUF score, 1.74, which puts it in group 6 of 6, group 1 being the genes least tolerant of losing a copy. Missense variants: 96 observed, 116.26 expected, observed/expected ratio (o/e) 0.83, 90% interval 0.7 to 0.98. Synonymous variants: 42 observed, 46.94 expected, observed/expected ratio (o/e) 0.89, 90% interval 0.7 to 1.16.
Homologues: Orthologues: chimpanzee COA4 (100% identical), macaque COA4 (93% identical), mouse Coa4 (87% identical), rat Coa4 (87% identical), guinea pig COA4 (84% identical), rabbit COA4 (84% identical), dog COA4 (83% identical), pig COA4 (82% identical), zebrafish coa4 (40% identical).
Diseases named in the same sentence as COA4 in open-access papers:
COA4 is named in the same sentence as 23 diseases in open-access papers, as found by Europe PMC text mining. Sharing a sentence is not in itself a finding about the gene and the disease. The quoted sentences say what the papers report.
autoimmune myocarditis (1 paper, 2022). Autoimmune myocarditis is an autoimmune disease that affects the heart. "It is possible that the potential source for COA4 could be the heart, since autoimmune myocarditis induced with Myhc-α led to the detection of COA4, albeit at a low level." (PMID 36101433, 2022). "To further investigate whether tissue damage is critical for producing COA4 and PIK3AP1 antibodies, we used the autoimmune myocarditis models induced with Myhc-α 334–352 or SERCA2a 971–990." (PMID 36101433, 2022).
Autoimmunity (1 paper, 2022). The occurrence of an immune reaction against the organism's own cells or tissues. "As additional evidence for the contribution of mitochondrial autoimmunity to breast carcinogenesis, autoantibodies in BC sera were found to target coding and noncoding regions of the COX7A2 gene and 3′-UTR of COA4." (PMID 37082114, 2022).
colorectal cancer (1 paper, 2022). A primary or metastatic malignant neoplasm that affects the colon or rectum. "Although the cancer-based study of COA4, a mediator protein in the assembly process of the cytochrome c oxidase complex, is lacking, overexpression of its related protein (COA1) has also been shown in colorectal cancer." (PMID 35818360, 2022).
Leigh syndrome (1 paper, 2024). A progressive neurological disease defined by specific neuropathological features associating brainstem and basal ganglia lesions. "PNE also caused the downregulation of Senp8, which is involved in neural development, and Coa4 which encodes a cytochrome c oxidase (COX) assembly factor whose downregulation may be linked to Leigh Syndrome or other related neurological disorders." (PMID 39574597, 2024).
lung squamous cell carcinoma (1 paper, 2025). "Although COA4 was also overexpressed in lung squamous cell carcinoma, no significant survival correlation was observed in this subtype, thereby focusing our investigation on LUAD." (PMID 40936169, 2025).
metastatic tumors (1 paper, 2025). "Given our previous findings implicating COA4 in mitochondrial OXPHOS and emerging evidence indicates that metastatic tumors exhibit high OXPHOS capacity,[13b] we investigated the role of mitochondrial metabolism in COA4‐mediated invasion and migration." (PMID 40936169, 2025).
pancreatic adenocarcinoma (1 paper, 2025). "Moreover, our in vitro and in vivo findings in pancreatic adenocarcinoma—a tumor type with one of the highest KRAS mutation rates—further indicate that COA4 knockdown suppresses metastasis." (PMID 40936169, 2025).
pancreatic cancer (1 paper, 2025). "Furthermore, in pancreatic cancer cells, scCOA4 overexpression partially reversed the loss of invasion and migration following COA4 knockdown." (PMID 40936169, 2025).
cancer (3 papers, 2022 to 2025). A tumor composed of atypical neoplastic, often pleomorphic cells that invade other tissues. "Given the critical role of OXPHOS in tumor proliferation and metastasis, we next investigated the expression pattern and clinical relevance of COA4 in cancers, particularly in LUAD." (PMID 40936169, 2025). "Taken together, our findings highlight COA4 as a critical target for the treatment of KRAS mutant‐driven cancer metastasis." (PMID 40936169, 2025). "Thus, COA4 represents a potential therapeutic target for inhibiting metastasis in KRAS‐driven cancers." (PMID 40936169, 2025). "Here, we showed that natural peptides from T. stans inhibited the growth, migration and invasion of A549 cells by suppressing the expression of cancer-promoting proteins (NCBP2, AMD, MER34, ENC1, and COA4)." (PMID 35818360, 2022). "The volcano plot revealed that the cancer-promoting proteins (NCBP2, AMD, MER34, ENC1, and COA4) were down-regulated, while the secretory glycoprotein (A1BG) and ROS-reducing protein (ASB6) were up-regulated in the treatment group." (PMID 35818360, 2022). "The cancer-promoting proteins (NCBP2, AMD, MER34, ENC1, and COA4) were suppressed, while the secretory glycoprotein (A1BG) and ROS-reducing protein (ASB6) were overexpressed in the treatment group." (PMID 35818360, 2022).
infection (1 paper, 2022). The state of being infected such as from the introduction of a foreign agent such as serum, vaccine, antigenic substance or organism. "Sera collected from infected or naïve animals on day 21 post-infection were analyzed for their reactivity to COA4 and PIK3AP1, with CVB3 VP1 and KLH as controls." (PMID 36101433, 2022). "Together, our data suggested that CVB3 infection leads to the production of autoantibodies to COA4 and PIK3AP1 but raised a question whether such reactivity could be seen in infections caused by other CVB serotypes." (PMID 36101433, 2022). "To determine whether COA4- and PIK3AP1-reactive antibodies are specific to CVB3 or whether their production can be expected in other serotype infections, we used sera from CVB4-infected mice for ELISA." (PMID 36101433, 2022). "Given these similarities, we believe that the pathogenetic pathways for the induction of IgG2a antibodies for COA4 and PIK3AP1 may be similar in CVB3 and CVB4 infections." (PMID 36101433, 2022).
tumor (1 paper, 2025). "Additionally, single‐cell sequencing data associated elevated COA4 expression with advanced pathological stages and poor tumor differentiation." (PMID 40936169, 2025). "Collectively, these findings suggest that defective mitochondrial import of COA4 attenuates its ability to drive mitochondrial oxidative phosphorylation, thereby limiting its pro‐metastatic capacity in tumor cells." (PMID 40936169, 2025). "To investigate this, we examined COA4‐mediated regulation of tumor cell migration through cytoplasmic protein interactions." (PMID 40936169, 2025). "Mechanistically, COA4 enhances tumor cell migration through dual pathways: within mitochondria, it boosts oxidative phosphorylation; in the cytoplasm, it binds and activates CDC42 to stimulate pseudopodia formation." (PMID 40936169, 2025). "Overexpression of E2F1 enhances tumor cell invasion and migration, whereas COA4 knockdown mitigates the malignant phenotypes induced by E2F1." (PMID 40936169, 2025). "Analysis of tumor COA4 expression levels revealed that deceased LUAD patients had significantly higher levels than surviving patients." (PMID 40936169, 2025). "Mechanistically, COA4 enhances tumor cell metastasis by upregulating mitochondrial OXPHOS and by interacting with CDC42 to activate its activity." (PMID 40936169, 2025). "Given that hypoxia and nutrient deprivation characterize the tumor microenvironment, we first assessed COA4 expression under low oxygen and low glucose conditions." (PMID 40936169, 2025). "In multiple KRAS‐mutant tumor cell lines, COA4 is consistently upregulated, and its knockdown partially reverses KRAS‐induced invasion and migration, establishing COA4 as a critical downstream effector of KRAS in promoting tumor metastasis." (PMID 40936169, 2025). "Immunohistochemical analysis of a tissue microarray containing 75 paired LUAD and adjacent normal tissues revealed pronounced upregulation of COA4 in tumor samples." (PMID 40936169, 2025). "In this study, we did not address whether combined inhibition of oxidative phosphorylation and CDC42 affects metastasis in COA4‐null tumor cells." (PMID 40936169, 2025). "Our data also reveal that COA4 is highly expressed in various tumor cells." (PMID 40936169, 2025). "Therefore, to resolve this question, future studies will utilize PDOs established from COA4‐null clinical tumor specimens." (PMID 40936169, 2025). "Moreover, knockdown of COA4 or pharmacological inhibition of COX or OXPHOS significantly suppresses tumor cell invasion and migration, suggesting that COA4 promotes metastasis by enhancing mitochondrial oxidative metabolism." (PMID 40936169, 2025). "To determine whether COA4 regulates tumor cell migration through CDC42, we assessed the impact of altered COA4 expression on CDC42 protein levels and activity." (PMID 40936169, 2025). "Functionally, yeast COA4 is capable of regulating mitochondrial COX activity and OXPHOS in human cells and even interacts with human CDC42 to facilitate tumor cell metastasis, underscoring its evolutionary conservation." (PMID 40936169, 2025). "Collectively, these results establish COA4 as a novel oncogenic candidate and prognostic biomarker in LUAD, characterized by tumor‐specific overexpression, stage‐dependent elevation, and a strong association with adverse clinical outcomes." (PMID 40936169, 2025). "To investigate the role of COA4 in tumor cell extravasation in vivo, we performed lung dissections at 4 and 24 h post‐tail vein injection of GFP+ A549 cells overexpressing COA4 in nude mice." (PMID 40936169, 2025). "Moreover, multiple tumor types—such as PAAD and COAD, where COA4 is highly expressed—also exhibit a positive correlation between E2F1 and COA4." (PMID 40936169, 2025). "Additionally, under hypoxic or nutrient‐deprived conditions, modulation of COA4 does not alter LUAD cell proliferation, although its in vivo effects on tumor growth through modulation of the immune microenvironment cannot be ruled out." (PMID 40936169, 2025).
COA4 also shares sentences with these, for which no sentence is quoted: breast carcinoma (3 papers); bone cancer (1); clear cell renal cell carcinoma (1); colon adenocarcinoma (1); dilated cardiomyopathy (1); hepatocellular carcinoma (1); myocarditis (1); neurological disorders (1); Pan (1); pancreatic ductal adenocarcinoma (1); prostate carcinoma (1); Stroke (1).